U3 (Small nucleolar RNA U3 )
Synonyms: LOC124902847
Gene: Small nucleolar RNA gene on chromosome 11 (32,081,764 to 32,081,973, forward strand). Ensembl gene ENSG00000212551.
Gene Ontology:
Biological process: RNA processing
Cellular component: nucleolus
Homologues: Orthologues: chimpanzee U3 (99% identical), macaque U3 (87% identical). Paralogues in human: U3 (80% identical), SNORD3P1 (80% identical), SNORD3E (76% identical), U3 (76% identical), SNORD3G (75% identical), U3 (75% identical), U3 (74% identical), U3 (73% identical), U3 (72% identical), SNORD3D (72% identical), U3 (71% identical), SNORD3H (71% identical), and 11 more.